CYP27A1 (cytochrome P450 family 27 subfamily A member 1)
Diseases named in the same sentence as CYP27A1 in open-access papers (continued):
Sharing a sentence is not in itself a finding about the gene and the disease.
Obesity (9 papers, 2018 to 2025). Accumulation of substantial excess body fat. "The influence we found of CYP27A1 polymorphism on these fundamental inflammatory players in obesity, including LTL, would underline the importance of this enzyme not only in cholesterol removal, via reverse transport, but also in the consequent aging response." (PMID 29951035, 2018). "Our research on CYP27A1 polymorphism opens new perspectives in investigation of the adverse health effects of obesity and in identifying persons at higher risk to develop T2D and CVD on which better converge preventive measures." (PMID 29951035, 2018). "Paediatric obesity was associated with compromised expression of VDR-controlled gene networks in the adipose tissue of children and lower expression of CYP27A1, which is involved in the initial activation of Vit-D3." (PMID 36443525, 2022). "In contrast, Cyp7a1 KO mice are also resistant to HFD-induced obesity, fatty liver, and insulin resistance due to induction of the alternative pathway Cyp27a1 and Cyp7b1 and the resultant increased production of the hydrophilic MCA." (PMID 35614477, 2022). "Vitamin D metabolizing enzyme expression (Cyp2r1, Cyp27a1, and Cyp2j3) was affected by high fat diet-induced obesity, which may partially explain the mechanisms of the modified vitamin D endocrine system related to obesity." (PMID 33195370, 2020). "CYP27A1 has the potential to act both as susceptibility marker in T2D and CVD development and as a key event in the chain of events connecting obesity to T2D and CVD development, representing a new possible target in personalized preventive medicine of chronic degenerative diseases." (PMID 29951035, 2018). "Our study supports evidence that CYP27A1 genetic characterization identifies persons at higher risk to develop CVD and T2D, on which better converge preventive measures, and opens new perspectives on mechanisms that link obesity with aging-related disorders." (PMID 29951035, 2018). "In addition, the clear significant role of CYP27A1 on the relationship between BMI and LTL attrition adds further insight into mechanism linking obesity with aging." (PMID 29951035, 2018).
cholestasis (8 papers, 2018 to 2025). Impairment of the bile flow caused by obstruction within the liver, or outside the liver in the bile duct system. "Moreover, PM2.5 significantly increased the expression of core genes associated with the biosynthesis (Cyp7a1, Cyp27a1, Baat, and Bacs) and regulation (Shp, Fgfr4) of primary bile acids, suggesting that cholestasis is an important cause of PM2.5 hepatotoxicity." (PMID 39195689, 2024). "FXR/SHP double knockout mice exhibited cholestasis and liver injury at 3 weeks of age, while a significant reduction in CYP27A1 gene expression was observed." (PMID 34867343, 2021). "We supposed that a decrease in the mRNA level of CYP27A1 was an adaptive reaction when cholestasis had formed." (PMID 34776958, 2021). "CSA, a well-known inducer of cholestasis, downregulated gene expression of CYP7A1, CYP27A1, BAAT, HNF4A, and INSIG1, while it upregulated ACAT2 and CCL20 gene expression." (PMID 38953992, 2024). "In accordance with the decrease in FGF19 in patients with cholestasis, BA-synthesized enzymes, including CYP7A1, CYP8B1, and CYP27A1, increased significantly in the liver." (PMID 30504803, 2018).
lung carcinoma (8 papers, 2011 to 2024). "We observed that CYP27A1 expression levels were downregulated in lung cancer cells (A549, NCI-H1650, and NCI-H1299) compared with 16HBE cells (p < 0.001)." (PMID 37817081, 2023). "We genotyped 296 SNPs in CYP2R1, CYP27A1, CYP27B1, CYP24A1, and VDR and observed associations between 27 SNPs and lung cancer status after the adjustment for age, gender, and race, all of which had passed the Hardy–Weinberg equilibrium assessment." (PMID 29726119, 2018). "To evaluate possible actions of 27HC in lung cancer pathogenesis, we determined the expression levels of CYP27A1, CYP7B1, ERα, and ERβ in a variety of lung cancer and normal lung cell lines." (PMID 30190703, 2018). "The expression of 27HC-generating enzyme CYP27A1 is higher in lung cancer cells than in normal lung cells." (PMID 30190703, 2018). "Since lung tumor cells have higher expression of 27HC-generating CYP27A1, it is plausible that endogenous 27HC production affects ERβ (+) lung cancer cell proliferation." (PMID 30190703, 2018). "Thus, it is reasonable to assume that higher CYP27A1 expression reflects higher 27HC production in lung cancer cells, and also there are reports showing effective CYP27A1 knockdown and consequent decrease of its protein expression." (PMID 30190703, 2018). "We further genotyped 296 SNPs in the same subjects (N = 761) in CYP2R1, CYP27A1, CYP27B1, CYP24A1, and VDR genes directly involved in vitamin D metabolism, with an objective to elucidate variants that may modulate vitamin D levels, thereby potentially explaining their associations with lung cancer." (PMID 29726119, 2018). "Although lung cancer cells have elevated gene expression of 27HC-producing enzyme CYP27A1, endogenously produced 27HC was not the major factor involved in the 27HC-induced cell proliferation." (PMID 30190703, 2018). "Consequently, CYP27A1 has the potential to serve as a prognostic marker for LUAD patients, providing a foundation for further investigation into its role in the development and progression of lung cancer." (PMID 37817081, 2023). "Interestingly, although the expression of CYP27A1 is higher in lung cancer cells than in normal lung cells, endogenously produced 27HC did not alter lung cancer cell proliferation in this study." (PMID 30190703, 2018).
cataract (7 papers, 2022 to 2025). Partial or complete opacity of the crystalline lens of one or both eyes that decreases visual acuity and eventually results in blindness. "Whether heterozygous variant in the CYP27A1 gene may lead to bilateral cataracts without the full CTX phenotype, as reported here for one patient, needs further examination." (PMID 36514115, 2022).
cerebellar ataxia (7 papers, 2019 to 2025). A neurological syndrome characterized by clumsy and uncoordinated movement of the limbs, trunk, and cranial muscles. "In a 48 year-old male (HA102) affected by cerebellar ataxia, pyramidal signs, sensorimotor polyneuropathy, cognitive impairment and lens opacity, a homozygous CYP27A1 splice site variant was identified." (PMID 40208338, 2025). "Mutations in CYP27A1 cause a rare lipid storage disorder (cerebrotendinous xanthomotosis) with intellectual disabilities, dementia, ataxia, and epilepsy, among other systemic symptoms." (PMID 35625841, 2022). "The most predominant mutations in CYP27A1 were c.410G > A and c.379C > T, and the most common clinical manifestations were pyramidal signs, xanthomatosis, cerebellar ataxia, and cognitive impairment." (PMID 31796091, 2019). "In the Chinese population, the most predominant mutations in the CYP27A1 gene were c.410G > A (p.R137Q) and c.379C > T (p.R127W), the most frequent clinical manifestations were pyramidal signs, xanthomatosis, cerebellar ataxia, and cognitive impairment." (PMID 31796091, 2019). "Furthermore, three patients carrying homozygous compound heterozygous CYP27A1 mutations causing CTX exhibited clinical symptoms such as ataxia, cataract, muscle atrophy, peripheral neuropathy, epilepsy, and pescavu." (PMID 37237429, 2023). "In humans, complete CYP27A1 deficiency leads to nodule formation in the brain which may lead to dementia, cerebellar ataxia, and spinal cord paresis." (PMID 35948598, 2022).
vitamin D deficiency (7 papers, 2016 to 2025). A nutritional condition produced by a deficiency of VITAMIN D in the diet, insufficient production of vitamin D in the skin, inadequate absorption of vitamin D from the diet, or abnormal conversion of vitamin D to its bioactive metabolites. "Mutations in the CYP27A1 gene can lead to genetic vitamin D deficiency, which typically responds poorly to the usual vitamin D deficiency treatment." (PMID 39457152, 2024). "In the present study, we found that vitamin D deficiency resulted in higher expression of CYP27A1 and CYP27B1, both of which were downregulated when Vitamin D, folic acid, and vitamin B12 were supplemented in the diets." (PMID 36615790, 2022). "The pathogenesis of vitamin D deficiency is possibly related to downregulation of synthetic hydroxylase CYP27A1 and upregulation of degrading CYP 24A1 in cirrhotic patients." (PMID 27399065, 2016). "Given vitamin D and 27-OHC have been confirmed to be associated with AD, we explored whether vitamin D deficiency affects AD by regulating the expression of CYP27A1." (PMID 36615790, 2022). "Since CYP27A1 participates in both 27-OHC synthesis and vitamin D signaling pathways, whether vitamin D deficiency affects learning and memory ability by regulating CYP27A1 expression and 27-OHC metabolism, remains unknown." (PMID 36615790, 2022). "This study suggests that CYP27A1 expression may be involved in the mechanism of learning and memory impairment induced by vitamin D deficiency." (PMID 36615790, 2022). "A previous study using high-fat diet animal models found that vitamin D deficiency could also upregulate the expression of CYP27A1, and vitamin D supplements reversed it, which suggests that there may be an interaction between high cholesterol and vitamin D." (PMID 36615790, 2022). "Hence, we hypothesized that vitamin D deficiency may lead to a decline in learning and memory ability by affecting CYP27A1." (PMID 36615790, 2022). "Vitamin D intervention can downregulate the expression of CYP27A1, then reduce the levels of 27-OHC, which then reverses the decline in learning and memory ability induced by vitamin D deficiency." (PMID 36615790, 2022). "In summary, the present study indicated that vitamin D deficiency was closely associated with learning and memory impairment in mice, probably in part by inducing 27-OHC metabolism disorders through upregulating the expression of CYP27A1." (PMID 36615790, 2022). "To study the possible mechanisms whereby vitamin D deficiency worsens with increased severity of liver dysfunction, we measured hydroxylases protein levels of CYP2R1, CYP27A1 (key enzymes in vitamin D synthesis) and CYP24A1 (key enzyme in vitamin D degradation) in 94 out of 345 subjects." (PMID 27399065, 2016). "In addition, the vitamin D metabolizing enzymes (CYP2R1, CYP27A1, and CYP27B1) are also widely expressed in Leydig cells of the testis, and vitamin D deficiency may result in reduced hypogonadism." (PMID 40365228, 2025).
bladder cancer (6 papers, 2022 to 2025). "CYP27A1 was reported to prevent bladder cancer cell proliferation via regulation of cholesterol metabolism." (PMID 37817081, 2023). "Cholesterol availability promotes bladder cancer cell proliferation in vitro, and CYP27A1 activity leads to 27-hydroxycholesterol production and decreased cholesterol levels, thus inhibiting cancer cell proliferation." (PMID 37508912, 2023). "Research indicates that CYP27A1 overexpression promotes 27-HC production and significantly suppresses bladder cancer cell growth, suggesting that CYP27A1 overexpression may represent a potential therapeutic strategy for bladder cancer." (PMID 40755754, 2025). "Additionally, research has found that in bladder cancer, cytochrome P450 family 27 subfamily A member 1 (CYP27A1) inhibits the proliferation of bladder cancer cells by regulating cholesterol homeostasis." (PMID 40722703, 2025). "Finally, intersecting these key genes with risk-consistent genes yielded eight immune-related genes that were negatively associated with bladder cancer risk: LIMS2, TP53INP2, IRAK3, STX2, CYP27A1, IL11RA, KCNMB1, and PDLIM7." (PMID 40755754, 2025). "Based on the findings of this study and the existing literature, we speculated that CYP27A1 might affect the development of bladder cancer by regulating 27-HC levels." (PMID 40755754, 2025). "Although no clinical therapies directly targeting CYP27A1 currently exist, its regulatory role in the tumor microenvironment suggests its potential value as a predictive biomarker for targeted therapy efficacy in bladder cancer." (PMID 40755754, 2025).
Hypercholesterolemia (6 papers, 2017 to 2025). An increased concentration of cholesterol in the blood. "A confirmed diagnosis requires elevated cholestanol levels, the presence of a pathogenic CYP27A1 variant in a homozygous or compound heterozygous state, and the exclusion of differential diagnoses such as familial hypercholesterolemia, sitosterolemia, and obstructive biliary tract diseases." (PMID 40710868, 2025). "A minimal amount of cholesterol is converted into 27-OHC by the hydroxylase CYP27A1, but most of it is derived from the peripheral circulation, and its influx in the brain increases under conditions of hypercholesterolemia that alter BBB permeability." (PMID 38671883, 2024). "Cyp27a1 gene expression in circulating monocytes is also upregulated in the setting of hypercholesterolemia." (PMID 37491347, 2023). "We show that the majority of lesion macrophage accumulation in the setting of hypercholesterolemia is surprisingly dependent on macrophage cyp27a1, and that this is related to the promotion of monocyte recruitment prompted by endothelial activation." (PMID 37491347, 2023). "Thus, in the setting of hypercholesterolemia, endothelial cell adhesion molecule expression and leukocyte-endothelial cell adhesion are promoted by macrophage cyp27a1." (PMID 37491347, 2023). "In the context of HCD induced hypercholesterolemia, pulmonary CYP27A1 expression increased in the HCD fed mice compared to the ND fed mice, suggesting a highly possibility that CYP27A1 mediated pulmonary cholesterol efflux might provide considerable amounts of metabolites for the activation of LXRs." (PMID 28680122, 2017). "This revealed that macrophages and monocytes are the immune cell types expressing the most cyp27a1, and that cyp27a1 expression is increased in macrophages and not in other immune cells in the setting of greater hypercholesterolemia." (PMID 37491347, 2023). "We now demonstrate that the pharmacologic inhibition of cyp27a1 in the setting of hypercholesterolemia is antiatherogenic, possibly revealing a means to intervene against hypercholesterolemia-related inflammation without disturbing innate or adaptive immune responses." (PMID 37491347, 2023).
Insulin resistance (6 papers, 2018 to 2022). Increased resistance towards insulin, that is, diminished effectiveness of insulin in reducing blood glucose levels. "Chemokine (C-C motif) ligand 21 (CCL21), CYP27A1, RPRM, and CPB1 are novel biomarkers for the development of insulin resistance." (PMID 30678306, 2019). "The ability to induce the Cyp27A1 pathway may therefore be an important protective mechanism, particularly in ‘pre-diabetic’ individuals characterised by low levels of dysfunctional HDL, in whom insulin resistance requires a compensatory phase of hyperinsulinaemia to maintain normoglycaemia." (PMID 30819824, 2019).
xanthoma (6 papers, 2014 to 2024). A non-neoplastic disorder characterized by a localized collection of histiocytes containing lipid. "These four probands predominantly presented with pyramidal signs, nonetheless two of them lacking of the typical symptoms like xanthomas illustrated patients only presented with pure and complicated HSP should not omit the investigation of CYP27A1 gene mutations." (PMID 32714376, 2020). "The CYP27A1 gene knockout mice do not present with xanthomas in brain or tendon." (PMID 25424010, 2014).
colorectal cancer (5 papers, 2016 to 2025). A primary or metastatic malignant neoplasm that affects the colon or rectum. "Consistently, it was previously reported that Cyp27a1 is highly expressed in the patients with colorectal cancer, hinting to a causal link among Cyp27a1, BAs, and the development of colon cancer." (PMID 28969019, 2017). "Consistently, human colorectal cancer specimens exhibited reduced levels of CYP27A1, LXR target genes, and B and CD8 T cell gene signatures." (PMID 39567700, 2025). "By using quantitative real‐time polymerase chain reaction (qRT‐PCR), we analyzed the expression ratio of CYP2R1, CYP27A1 and CYP27B1 genes within the vitamin D metabolic pathway in a total of 75 colorectal cancer (CRC) tissues compared to the adjacent tissues." (PMID 33058307, 2021). "Immunohistochemistry was performed on a colorectal cancer tissue microarray containing 650 primary colorectal cancers using monoclonal antibodies to CYP2R1, CYP7B1, CYP8B1, CYP27A1, CYP39A1, CYP46A1 and CYP51A1, which we have developed." (PMID 27341022, 2016). "This study has profiled the expression of the cholesterol metabolising enzymes CYP2R1, CYP7B1, CYP8B1, CYP27A1, CYP39A1, CYP46A1 and CYP51A1 in primary colorectal cancer tissue using a well-characterised cohorts of colorectal cancers." (PMID 27341022, 2016).
dementia (5 papers, 2019 to 2023). Loss of intellectual abilities interfering with an individual's social and occupational functions. "Cedazo-Minguez and co-workers have suggested inhibiting CYP27A1, the enzyme responsible for converting cholesterol to 26-HC may be a preventative strategy to reduce the risk of dementia or to improve therapies to restore neuronal function." (PMID 30936243, 2019). "While 26-HC and CYP27A1 may be associated with the cause of dementia, CYP46A1 may have a therapeutic potential towards AD." (PMID 30936243, 2019). "Therefore, reducing the overproduction of 27-OH using inhibitors for the enzyme responsible for converting cholesterol to 27-OH, Cyp27A1, may be a possible preventive strategy to reduce the risk of dementia or to improve therapies restoring neuronal function in neurodegeneration." (PMID 30395175, 2019).
diabetes (5 papers, 2018 to 2025). "Some common polymorphisms in CYP27A1 gene (rs4674345, rs4674338) are associated with premature aging, type 2 diabetes mellitus risk in obese population and higher cardiovascular risk." (PMID 36619921, 2022). "Since the conversion of vitamin D to 25OHD predominantly catalyzes two cytochrome P450 isoforms (mitochondrial CYP27A1 and microsomal CYP2R1), it was useful to determine whether a significant 25OHD deficiency in diabetes is associated with any changes in the expression of these enzymes." (PMID 29552033, 2018). "Specifically, genes such as CCL17, CD163, APOE, CYP27A1, and STAB1, some of which are recognized as anti-atherogenic and anti-inflammatory factors in diabetes patients, were identified within this module." (PMID 38658734, 2024).
hyperlipidemia (5 papers, 2019 to 2026). "Second, alternative causes of hyperlipidemia should be considered—four unique P and LP variants in other genes (CYP27A1, ABCG5, ABCG8, and LIPA) were found in seven patients (2% of all patients with positive monogenic variant), which increases the overall diagnostic yield to 23.6%." (PMID 39769230, 2024). "The present study demonstrates that hyperinsulinaemia and hyperlipidaemia in normoglycaemic genetically obese male rodents is accompanied by increased protein expression of Cyp27A1, ADXR and TSPO, and nuclear transcription factor LXRα in pancreatic tissue." (PMID 30819824, 2019).